EGF (epidermal growth factor)
Diseases named in the same sentence as EGF in open-access papers (continued):
Sharing a sentence is not in itself a finding about the gene and the disease.
Premature ovarian insufficiency (3 papers, 2020 to 2023). Amenorrhea due to loss of ovarian function before the age of 40. "Using a liquid‐solid phase transition bio‐gel as a carrier, our study showed that EGF was functional to improve the activation of dormant primordial follicles in vivo by an ovarian topical administration approach in both normal and inducible premature ovarian insufficiency (iPOI) mice." (PMID 32997412, 2020). "By establishing an inducible premature ovarian insufficiency (POI) mouse model through selectively ablating growing follicles in Zp3‐Cre;iDTR mice, we further revealed that our in vivo EGF treatment system improved primordial follicle activation and ovulation of POI ovaries significantly." (PMID 32997412, 2020).
reflux esophagitis (3 papers, 2014 to 2022). "In another, EGF expression was higher in the area of reflux esophagitis than in the proximally located areas with normal epithelium." (PMID 35564692, 2022). "It has previously been found that luminal release of EGF was significantly lower in patients with EE compared with controls during perfusion with HCl and this was considered as one of the potential mechanisms leading to damage of the esophageal mucosa during gastroesophageal reflux episodes." (PMID 35564692, 2022).
salivary gland tumors (3 papers, 2015 to 2022). "The insensitivities of the salivary gland tumors or tumor cells to cetuximab treatment were not due to the lack of activity of the cetuximab we used, since cetuximab partially inhibited EGF-induced ERK/AKT phosphorylation in serum-starved tumor cells." (PMID 26289340, 2015). "The resulting candidate genes as possible therapeutic targets were FN1, SPP1, EGF, and ERBB2, and all those genes had been tested as a target in other neoplasm kinds but not salivary gland neoplasm." (PMID 36146635, 2022).
schwannoma (3 papers, 2013 to 2026). A benign, usually encapsulated slow growing tumor composed of Schwann cells. "However, its function as an activator of cell proliferation cannot be ruled out, since EGFR may still be signaling downstream in a merlin-absent context, despite the lack of proliferation of the human schwannoma cells following exposure to the ligand EGF, in contrast to non-tumoral vestibular cells." (PMID 23354516, 2013).
seminoma (3 papers, 2015 to 2022). A radiosensitive malignant germ cell tumor found in the testis (especially undescended), and extragonadal sites (anterior mediastinum and pineal gland). "TGF-β1, together with EGF and FGF4, synergistically contribute to differentiation of seminoma cells into the mixed non-seminoma-like cell type." (PMID 31842336, 2019). "In previous studies, we demonstrated that the seminoma cell line TCam-2 differentiates into a mixed non-seminoma, when being cultivated in murine embryonic fibroblast conditioned medium supplemented with FGF4 /Heparin or in a combination of FGF4 /TGF-B1 /EGF, which mimics a somatic microenvironment." (PMID 26226633, 2015).
skin rashes (3 papers, 2020 to 2025). "Additionally, isotretinoin was also recommended in the management of other types of skin rashes induced by oncologic medications, such as epidermal growth factor inhibitors, BRAF inhibitors, MEK inhibitors, and mTOR inhibitors." (PMID 39963639, 2025). "The tissue concentrations of EGF and EGF receptors are regulated by sex hormones such as estrogen and testosterone, which may contribute to sex differences in the development of skin rashes induced by anti-EGFR antibodies." (PMID 34441007, 2021). "Some studies even suggest that the appearance of skin conditions such as epidermal growth factor inhibitor (EGFRI) toxicity‐related skin rash could potentially be a predictive marker for treatment efficacy, since they reflect drug concentration and activity." (PMID 33015988, 2020).
tongue cancer (3 papers, 2019 to 2025). A malignant neoplasm affecting the tongue. "Epidermal growth factor (EGF) is able to suppress and reduce tumor expression of the EGF receptor, which is overexpressed in a variety of tumor cells, including those that cause breast and tongue cancer." (PMID 37814270, 2023). "At proteomic level, TBM-02 cell line supernatant demonstrated distinct levels of cytokines IL-6 and IL-8, and growth factors EGF, PECAM-1 and VEGF in comparison to AW13516 which is a tongue cancer cell line." (PMID 41410801, 2025).
type 1 diabetes (3 papers, 2021 to 2023). "Probably the early clues to the involvement of EGFR/ErbB receptors in diabetes-induced complications were the observation that excretion of EGF ligand was abnormal in many patients with diabetes and that EGF gene expression was elevated in the mesenteric artery of rats bearing type 1 diabetes." (PMID 34408653, 2021).
Uterine leiomyoma (3 papers, 2021 to 2023). The presence of a leiomyoma of the uterus. "The expression of various growth factors (EGF, IGF-1, TGF-β, and VEGF) was evaluated in uterine leiomyoma tissues." (PMID 36313223, 2022).
acute pancreatitis (2 papers, 2019 to 2024). An acute inflammatory process that leads to necrosis of the pancreatic parenchyma. "The administration of exogenous EGF inhibits the development of experimental acute pancreatitis in rats and accelerates the recovery in different models of acute pancreatitis." (PMID 30934722, 2019). "Also, endogenous EGF seems to be involved in the protection and healing of the pancreas in acute pancreatitis." (PMID 30934722, 2019).
adenomyosis (2 papers, 2016 to 2022). The growth of endometrial tissue inside the muscular wall of the uterine corpus. "In this review, we concentrated on VEGF, EGF, MMP2, IL-6, and TGF-β because we suspect that they may play a major role in the biological processes leading to the establishment and maintenance of adenomyosis." (PMID 26898650, 2016).
Alcoholic Liver Damage (2 papers, 2014 to 2023). "Previous studies have showed that epidermal growth factor, L-glutamine, oats supplementation, or zinc may reduce circulating endotoxin by preserving intestinal integrity in alcoholic liver disease." (PMID 25286027, 2014).
alopecia (2 papers, 2019 to 2023). Hair loss usually from the scalp. "EGF treatment showed significant reduction in chemotherapy-induced alopecia, where it decreased the chemotherapy-induced apoptosis of keratinocytes in hair matrix and retarded the progression of chemotherapy-induced alopecia." (PMID 32082154, 2019).
Alport syndrome (2 papers, 2015 to 2018). A rare renal disease characterized by glomerular nephropathy with hematuria progressing to end-stage renal disease (ESRD), frequently associated with sensorineural deafness, and occasionally with ocular anomalies. "To address this urgent need, we investigated if urinary EGF is associated with loss of kidney function and if it has prognostic value in patients with Alport syndrome, since urinary EGF has been reported previously as a prognostic marker in adult CKD progression." (PMID 29948307, 2018). "If and how EGF is actively involved in Alport syndrome tubular damage repair and regeneration in Alport syndrome remains to be further studied." (PMID 29948307, 2018).
Anorexia (2 papers, 2025). Lack of desire to eat (loss of appetite). "We identified three prognostic genes (EGF, BNIP3, TDGF1) associated with anorexia." (PMID 40495091, 2025).
anorexia nervosa (2 papers, 2019 to 2022). A disorder most often seen in adolescent females characterized by a refusal to maintain a minimally normal body weight, an intense fear of gaining weight, a disturbance in body image, and, in postmenarcheal females, the development of amenorrhea. "IL-1α, IL-10, EGF, and IFN-γ were altered individuals with anorexia nervosa (AN) and binge eating disorder (BED)." (PMID 31450770, 2019).
aphthous stomatitis (2 papers, 2023). "Salivary epidermal growth factor (EGF) has been shown to be beneficial in the treatment and prevention of recurring aphthous ulcers." (PMID 38114965, 2023). "The searches were completed by the medical subject heading terms considering "recurrent aphthous stomatitis" and "saliva" in combination with "EGF" or "VEGF" keywords." (PMID 37727361, 2023).
aplasia cutis congenita (2 papers, 2023 to 2025). Aplasia cutis congenita (ACC) is a rare skin disorder characterized by localized absence of skin that is usually located on the scalp but can occur anywhere on the body including the face, trunk and extremities. "A recent case report detailed the successful conservative treatment of a large aplasia cutis congenita defect in an infant with AOS using a recombinant human EGF gel, leading to complete healing and avoiding the need for surgery." (PMID 41516051, 2025).
Atrophy (2 papers, 2013 to 2025). Any weakening or degeneration, especially through lack of use. "For example, transcriptomic studies have demonstrated that reduced intrarenal epidermal growth factor (EGF) expression correlates with tubular atrophy and interstitial fibrosis (TA/IF), refining prognostic assessment within the same morphologic class." (PMID 41262438, 2025).
B-cell lymphoma (2 papers, 2021 to 2025). "The SAW biosensor with either a ST-quartz or LiTaO3 substrate, has been reported for the detection of biomarkers for the early diagnosis of cancer, such as the carcinoembryonic antigen (CEA), prostate-specific membrane antigen (PSMA), epidermal growth factor (EGF), B-cell lymphoma, and exosomes." (PMID 35056189, 2021).
bacteremia (2 papers, 2017 to 2020). "When we analyzed the impact of bacteremia on marker levels we only found bacteremia to be positively associated with EGF and eotaxin levels with moderate correlations." (PMID 28628613, 2017). "Only EGF and eotaxin showed a moderate positive correlation with bacteremia." (PMID 28628613, 2017). "However, a previous report examining the cytokine profiles of 144 healthy patients from five villages in Northern Peru that had suffered recent Bb outbreaks and/or were endemic for Carrión’s disease showed a moderate positive correlation between EGF levels and chronic Bb bacteremia." (PMID 32302357, 2020).
Barrett esophagus (2 papers, 2016 to 2022). Esophageal lesion lined with columnar metaplastic epithelium which is flat or villiform. "Our findings suggest several signaling pathways, including TGF-β, EGF, and their downstream genes as potential targets for further studies aimed at finding biomarkers for early diagnosis, detection and risk prediction in premalignant progression of Barrett’s esophagus." (PMID 27731371, 2016).
basal cell carcinoma (2 papers, 2020). A carcinoma involving the basal cells. "The combination of SHH and EGF leads to a synergistically activated growth response in basal cell carcinoma and tumor-initiating pancreatic cancer cells both in vitro and in vivo." (PMID 32341755, 2020). "Synergistic integration of SHH and EGF signaling has been identified as a critical step in oncogenic transformation, neural stem cell proliferation, and development of tumor types such as skin, prostate, pancreas, and basal cell carcinoma." (PMID 32341755, 2020).
beta cell tumor (2 papers, 2010 to 2020). "Betacellulin (BTC), a member of the epidermal growth factor (EGF) family, was originally isolated from mouse beta cell tumor (betaTC-3) as a growth–promoting factor and is known to be expressed in pancreatic α-cells, β-cells, and duct cells in adult humans." (PMID 33553143, 2020).
bladder transitional cell carcinoma (2 papers, 2013 to 2018). The most common morphologic subtype of urinary bladder carcinoma (over 90% of cases). "A recent study indicated that MASPIN-positive cells were resistant to EGF-induced EMT, suggesting that MASPIN may be involved in the EMT pathways in urothelial-bladder carcinoma." (PMID 23762858, 2013).
brain glioma (2 papers, 2010 to 2021). A malignant glioma that involves the brain. "The purpose of this study was to investigate the potential association between EGF +61G/A and brain glioma in a Chinese population." (PMID 20487573, 2010). "Variations of the EGF +61G/A (rs4444903) may lead to an alteration in EGF production and/or activity, which can result in individual susceptibility to brain glioma." (PMID 20487573, 2010).
bronchopulmonary dysplasia (2 papers, 2021 to 2022). Bronchopulmonary dysplasia is a chronic respiratory disease that results from complications related to lung injury during the treatment of infant acute respiratory distress syndrome in low-birth-weight premature infants or from abnormal lung development in older infants. "EGF is one of the growth factors associated with the pathogenesis of major respiratory outcomes of prematurity—bronchopulmonary dysplasia—through several pathways." (PMID 35328399, 2022). "Conversely, modified expression of growth factors, such as EGF, has been reported in pathological lung conditions such as bronchopulmonary dysplasia, bronchial asthma, and pulmonary fibrosis." (PMID 35328399, 2022).
carcinoid (2 papers, 2005 to 2022). "We here report the novel findings that HGF, EGF and PACAP all stimulate proliferation of carcinoid BON cells." (PMID 15846300, 2005). "PDGF, EGF, TGF, insulin-like growth factors and FGF recently have been demonstrated in gastrointestinal carcinoids, and these growth factors may play a central role in the genesis of SPMs in patients with carcinoid tumors." (PMID 36278575, 2022).
cardiomyopathies (2 papers, 2017). "Our results support it, showing that knocking down the potassium channel, which leads to a diabetic/cardiomyopathies related phenotype in Drosophila, has downstream effects activating EGF expression." (PMID 28676676, 2017). "Targeted therapies with human epidermal growth factor antibodies, tyrosine kinase inhibitors or vascular endothelial growth factor antibodies, and the antimetabolites also have shown to induce cardiomyopathy and myocardial ischemia." (PMID 29872712, 2017).
cataract (2 papers, 2023 to 2024). Partial or complete opacity of the crystalline lens of one or both eyes that decreases visual acuity and eventually results in blindness. "When UM patients’ aqueous humor was compared to those of subjects with cataracts, the results revealed greater amounts of IL-6, IL-8, EGF, bFGF, macrophage inhibitory factor (MIF), and MCP-1." (PMID 39596556, 2024). "Between Chinese patients with UM and control subjects with cataracts, significant differences were observed in the expression of numerous angiogenic, chemotactic, and inflammatory cytokines, such as IP-10, IL-6 and IL-8, NGF-β, PLGF-1, b-FGF, EGF, VEGF-A, and RANTES." (PMID 39596556, 2024).
cervical adenocarcinoma (2 papers, 2023 to 2025). An adenocarcinoma arising from the cervical epithelium. "Initial mechanistic studies on phosphorylation signaling and cholesterol depletion revealed that EGF-polystyrene nanoparticles exhibited cytotoxicity against human cervical adenocarcinoma HeLa cells via local enhancement of EGFR activity in membrane rafts." (PMID 41140511, 2025). "To evaluate the cytotoxicity induced by EGF polymeric nanoparticles, we first investigated the cellular responses, mechanism of action, and anti-cancer activities of EGF-NPs with PS as a carrier (EGF-PSNPs) using the HeLa human cervical adenocarcinoma cells." (PMID 41140511, 2025). "However, this was in contrast with a study of human cervical adenocarcinoma cells which revealed that EGF/EGF receptors increased S1P production by activating Sphk2 within the endoplasmic reticulum or Golgi apparatus." (PMID 37038210, 2023). "EGF-PSNPs exhibited anti-cancer activity against HeLa human cervical adenocarcinoma cells, but PEG-PSNPs without EGF were non-cytotoxic." (PMID 41140511, 2025).
chondrosarcoma (2 papers, 2019 to 2022). A malignant cartilaginous matrix-producing mesenchymal neoplasm arising from the bone and soft tissue. "To test this hypothesis, we examined whether SW1353 and HEMC-SS chondrosarcoma cells produce EGF." (PMID 31139331, 2019). "The results clearly show that HEMC-SS chondrosarcoma cells produce significant amount of EGF, whereas SW1353 cells did not produce detectable amount of this growth factor, therefore suggesting an autocrine loop in HEMC-SS chondrosarcoma." (PMID 31139331, 2019).
chorioamnionitis (2 papers, 2021 to 2022). A morphologic finding indicating inflammation of the fetal sac membranes. "Since preterm birth and PPROM may be complicated by intraamniotic infection and fetal inflammatory response syndrome, we investigated EGF levels associated with histological chorioamnionitis and fetal inflammatory response syndrome." (PMID 35328399, 2022). "Due to the significantly higher rate of histological chorioamnionitis and FIRS in extremely preterm and very preterm neonates, we investigated the association between median EGF levels with intraamniotic infection according to gestational age." (PMID 35328399, 2022). "Unexpectedly, we did not establish any EGF association with histological chorioamnionitis, FIRS, or inflammatory cytokines such as IL-6, TNF-α, and MMP-8." (PMID 35328399, 2022). "To investigate additional outcomes, such as whether EGF concentrations are affected by intraamniotic infection and inflammation, we analyzed EGF’s relationship to histological chorioamnionitis and fetal inflammatory response syndrome (FIRS)." (PMID 35328399, 2022). "An elevated level of cytokines IL-1β, IL-6, TNFα, IFNγ, EGF, MIP3α in patients with PROM and intra-amniotic infection." (PMID 34745106, 2021). "The analysis results confirmed that EGF concentrations in noninvasively obtained amniotic fluid were not significantly influenced by chorioamnionitis or FIRS in different gestational age groups." (PMID 35328399, 2022). "Furthermore, Varner’s findings that amniotic fluid EGF levels did not change by chorioamnionitis confirm our results." (PMID 35328399, 2022).
chronic pancreatitis (2 papers, 2016 to 2020). A chronic inflammatory process causing damage and fibrosis of the pancreatic parenchyma. "Metaplastic lesions of chronic pancreatitis patients regularly express high levels of the epidermal growth factor receptor (EGFR) family and their natural ligands EGF and TGFα." (PMID 26697077, 2016).
chronic viral hepatitis (2 papers, 2013 to 2024). "We also examined whether the EGF – HCC risk association differed across different risk profiles as determined by environmental exposures (use of tobacco or alcohol, viral hepatitis serologic status) or the Th1/Th2 genotypes." (PMID 23419149, 2013).
co-infection (2 papers, 2013 to 2023). "This might suggest that the performance of at least EGF and IL-1α might be influenced by HIV co-infection." (PMID 23691173, 2013).
corneal edema (2 papers, 2023). "And prednisolone acetate and recombinant human epidermal growth factor derivative eye drops were prescribed postoperatively to reduce corneal edema." (PMID 37312094, 2023).
coronary artery atherosclerosis (2 papers, 2016 to 2024). "The current study is the first large population-based study to investigate the association of the kidney damage biomarkers KIM-1, DKK-3, osteopontin, and EGF with two indices of coronary artery atherosclerosis." (PMID 39587192, 2024).
crescentic glomerulonephritis (2 papers, 2022 to 2024). A histopathologic term for a pattern of diseases characterized by extensive crescent formation in the glomeruli; patients present clinically with rapid deterioration of renal function, and possible progression to end-stage renal failure within weeks or months. "To explore the mechanism underlying glucocorticoids' inhibition of EGF signaling, we tested the effect of glucocorticoids on the expression of HB-EGF, an EGFR ligand that is known to be de novo induced in patients with RPGN but not non crescentic glomerulonephritis." (PMID 35223886, 2022).